AKT3 (AKT serine/threonine kinase 3)
Diseases named in the same sentence as AKT3 in open-access papers (continued):
Sharing a sentence is not in itself a finding about the gene and the disease.
gastric cancer (continued). "Previous studies have demonstrated that lncRNA NR2F1-AS1 can influence breast and gastric cancer progression by activating insulin-like growth factor-1 (IGF-1)/IGF-1R/ERK, MAP3K2, and AKT3, which crosstalk with AKT." (PMID 35283481, 2022). "CircRNA AKT3 upregulates PIK3R1 by inhibiting miR-198 to enhance cisplatin resistance (by inhibiting apoptosis and facilitating DNA damage repair) in gastric cancer." (PMID 35615158, 2022). "However, the specific role of AKT3 in the progression of gastric cancer is unknown." (PMID 34983559, 2022). "In stomach cancer, evidence had indicated that mir-195-5p is able to sensitize chemotherapeutic resistant gastric cancer cells to 5-fluorouracil and cisplatin by directly targeting ZNF139 and AKT3, respectively." (PMID 33811245, 2021). "For instance, circAKT3 (hsa_circ_0000199), which is derived from exons 8, 9, 10 and 11 of the AKT3 gene and highly expressed in DDP-resistant gastric cancer cells and tissues, plays a crucial role in DDP resistance of gastric cancer." (PMID 32192494, 2020). "We have previously identified AKT3 as a potential vulnerability in gastric cancers lacking CDH1 expression." (PMID 35406381, 2022). "Moreover, circ-AKT3, circ_0081143, and circ-FN1 were documented to enhance CDDP resistance of human gastric cancer cells." (PMID 32855967, 2020). "For example, circular RNA AKT3 could inhibit the expression of miR-198 and up-regulate PIK3R1 expression, then enhance cisplatin resistance in gastric cancer." (PMID 32499818, 2020). "Bioinformatic analysis of the TCGA STAD dataset revealed that AKT3, but not AKT1 or AKT2, is upregulated in the majority of E-cadherin-deficient gastric cancers." (PMID 31540244, 2019). "We have previously shown that AKT3, but not AKT1 or AKT2, is upregulated in gastric cancers with low CDH1 expression and have identified an E-cadherin-AKT synthetic lethal relationship." (PMID 35406381, 2022).
glioblastoma (33 papers, 2011 to 2025). The most malignant astrocytic tumor (WHO grade IV). "Circ-AKT3 encodes the 174aa protein AKT3-174aa, inhibiting glioblastoma cell proliferation, radiation resistance, and tumorigenicity." (PMID 40647484, 2025). "For example, PINT87aa and AKT3-A74aa, two peptides encoded by circRNAs, can interact with signal factors and inhibit glioblastoma tumorigenicity in glioblastoma." (PMID 33131025, 2021). "circ-AKT3 encoded a novel protein (AKT3-174aa), which decreased the proliferation and radiation resistance of glioblastoma cells." (PMID 33390857, 2021). "AKT3 was associated with glioblastoma; ELK1 participated in neurotrophin TRK receptor signaling pathway and FOXO4 can negatively regulate cell proliferation." (PMID 27903978, 2017). "Moreover, a novel tumor suppressor protein (AKT3-174aa) encoded by circular AKT3 RNA inhibits glioblastoma tumorigenicity." (PMID 37652905, 2023). "AKT3-174aa expression is lowered in glioblastoma cells and is negatively associated with the diagnosis of the disease, suggesting that it may be a potential biomarker." (PMID 35223470, 2022). "Circ-AKT3, a transcription variant from parental gene AKT3, had been found to be lowly expressed in glioblastoma tumor tissues and could encode a 174 amino acid novel protein named AKT3-174aa by utilizing overlapping start-stop codons." (PMID 36091137, 2022). "Furthermore, increased AKT3 mRNA levels were associated with increased patient survival and lower grade glioblastomas suggesting a more favourable outcome for these patients, whereas AKT1 and AKT2 expression was increased in higher grade tumours." (PMID 28082369, 2017). "In glioblastoma multiforme (GBM), AKT3-174aa ncPEP is encoded by hsa_circ_0017250/circAKT3, a circRNA that comprises exons 3–7 of the AKT3 gene." (PMID 39054345, 2024). "circRNA AKT serine/threonine kinase 3 (circ_AKT3) is derived from AKT3, which has been regarded to have a vital role in glioblastoma and clear cell renal cell carcinoma." (PMID 35233464, 2022). "AKT3-174aa overexpression inhibits glioblastoma cell proliferation, radiation resistance, and tumorigenicity." (PMID 32019587, 2020). "Akt3, found in glioblastoma, enhances tumor progression by activating DNA repair pathways, leading to enhanced survival of human glioblastoma cells following radiation or temozolomide treatment." (PMID 30374421, 2018). "It has been reported that the miR-610 repressed CCND2 and AKT3 leading to proliferation inhibition on human glioblastoma cells." (PMID 29228616, 2017). "In glioblastoma, it promotes the progression and knockdown of AKT3 suppresses the T98G cells invasiveness." (PMID 27903978, 2017). "In the T98G glioblastoma multiforme cell line, the expression of AKT3 or PI3KCA genes is downregulated by siRNAs that target their mRNAs and this leads to the upregulation of the BAX/BCL-2 mRNA expression ratio." (PMID 24967401, 2014). "In glioblastoma models, AKT3 gene amplification significantly increases the expression of DNA repair proteins, as evidenced by a significant increase in p-γ-H2AX foci and strong phosphorylation of ATM following γ-irradiation in AKT3-overexpressing cells compared with the empty vector group." (PMID 40725100, 2025). "The AKT3-174aa peptide, encoded by circ-AKT3 expressed in glioblastoma, can bind to PDK1 and reduce threonine phosphorylation at AKT308, thus participating in the inhibition process of glioblastoma." (PMID 39199340, 2024). "Recent research has confirmed this hypothesis by showing that elevated AKT3 expression may delay glioblastoma progression." (PMID 34209611, 2021). "Compared with normal brain tissue, AKT3-174aa is downregulated in glioblastoma tissue." (PMID 32019587, 2020). "However, in a separate study, AKT3 overexpression reduced cell-cycle progression and cell survival in human glioblastoma cell lines, and increased the tumour survival of mice with orthotopic injection of glioblastoma cells." (PMID 28082369, 2017).
glioblastoma (continued). "On the other hand, because amplification of Akt3 has also been reported in glioblastoma, we reason that elevated Akt3 expression may be crucial for brain tumor formation and progression." (PMID 21299869, 2011). "Circ-AKT3 regulates temozolomide (TMZ) resistance in glioblastoma (GBM) by regulating the phosphoinositide 3-kinase (PI3K)/protein kinase B (AKT) pathways and cancer stem cell characteristics." (PMID 41281941, 2025). "By using junction-specific primers, we explored circ-AKT3 expression patterns in several established GBM cell lines, glioblastoma-initiating cells (GICs) and a cohort of 38 GBM patient tissues as we previously reported." (PMID 31470874, 2019). "Immunofluorescence staining of glioblastoma cells transfected with Flag-tagged AKT3-174aa also supported the co-localization of AKT3-174aa with p-PDK1, suggesting that AKT3-174aa preferred to inhibit thr308 of AKT by interacting with p-PDK1." (PMID 36091137, 2022). "In vitro and in vivo experiments proved that AKT3-174aa, but not circ-AKT3, exerted a tumor-suppressive role in glioblastoma." (PMID 36091137, 2022). "Inhibiting AKT3 and PI3KCA enhanced chemotherapy sensitivity in glioblastoma multiforme cells." (PMID 28316978, 2017). "Further studies are warranted in order to determine whether targeting AKT3 and PI3KCA genes with siRNAs has a true potential for glioblastoma multiforme treatment in vivo." (PMID 24967401, 2014). "In the present study, AKT3 (PKBγ) and PI3KCA (p110α) were targeted with siRNAs in order to examine the inhibition of their signaling cascade on the growth, viability, proliferation of glioblastoma multiforme, and the induction of apoptosis." (PMID 24967401, 2014). "Therefore, blocking AKT3 and PI3KCA with suitable siRNAs offers a potential therapeutic strategy for controlling the growth of human glioblastoma multiforme cells." (PMID 24967401, 2014). "Thus, the knockdown of AKT3 and PI3KCA genes may offer a potential therapeutic solution for controlling the growth of human glioblastoma multiforme cells." (PMID 24967401, 2014). "In addition, the overexpression of AKT3-174aa diminishes glioblastoma cell proliferation, tumor growth, and radiation resistance, while its knockdown increases the malignant phenotypes, indicating that AKT3-174aa, but not circRNA itself, exerts a tumor-inhibiting role in glioblastoma cells." (PMID 35223470, 2022). "In glioblastoma, AKT2 and AKT3 but not AKT1 promote tumor progression, and alterations in the polarity of the PH domain and the regulatory domain were identified as responsible mechanisms for the isoform-specific effect." (PMID 33670586, 2021). "Similarly, circAKT3 encodes a 174aa protein (AKT3-174aa); AKT3-174aa (but not circ-AKT3) exerts a tumor-suppressive role by negatively regulating the phosphoinositide 3-kinase/protein kinase B (PI3K/Akt) signaling pathway in glioblastoma (GBM)." (PMID 34055634, 2021).
colorectal cancer (24 papers, 2008 to 2025). A primary or metastatic malignant neoplasm that affects the colon or rectum. "The elevated expression of AKT3 also indicates an increased activity of this pathway; furthermore, high AKT3 expression was associated with increased EMT of colorectal cancer cells, suggesting that loss of Tks4 may accelerate progression of this cancer type." (PMID 36674824, 2023). "To determine if AKT3 expression could be used to identify patients at risk of recurrence we analysed the expression of AKT3 in a publicly available cohort of colorectal cancer patients with microsatellite stable local disease (Stage I–III)." (PMID 33673003, 2021). "The AKT3 overexpression demonstrates increased activity of this pathway, and elevated AKT3 expression is correlated with the process of EMT in colorectal cancer cells." (PMID 38672463, 2024). "For instance, LINC02163 was demonstrated to regulate colorectal cancer cell function by miR-511-3p/AKT3 axis." (PMID 35392234, 2022). "In colorectal cancer, propofol inhibits cell proliferation and metastasis by regulating miR-124-3p.1/AKT3." (PMID 34983559, 2022). "Collectively all these results reveal that the RIMKLB gene has a positive association and correlation with AKT3, MPDZ, PKD2, and MAP1B to upregulate the gene expression to induce the development of colorectal cancer." (PMID 35444692, 2022). "Future research should point out if high AKT3 expression can be used to select colorectal cancer patients that have a poor prognosis but that could benefit from AKT3-targeted treatment." (PMID 33673003, 2021). "Another essential result of the study was that the inhibitory anti‐tumour effects of propofol on colorectal cancer cells could be reversed by suppressing miR‐124‐3p.1 expression or the overexpression of AKT3." (PMID 32596964, 2020). "Moreover, Li et al54 found that propofol inhibited the proliferation, migration and invasion of colorectal cancer cells by increasing the expression of miR‐124‐3p.1 and decreasing that of its target gene, AKT3." (PMID 32596964, 2020). "AKT1 may function as an oncogene and AKT3 as a tumor suppressor, and AKT mutations have been detected in human colorectal cancer (AKT2) and lung tumors (AKT1 and AKT3)." (PMID 24338765, 2014). "In addition, AKT3 was undetectable in colorectal cancer cells." (PMID 40279519, 2025). "Furthermore, our data suggests that high AKT3 expression in tumour cells may be used to identify poor prognosis colorectal cancer patients." (PMID 33673003, 2021). "AKT3 expression decreased after treatment, indicating that controlling EZH2 activity might moderate colorectal cancer progression." (PMID 38672463, 2024). "Moreover, in xenograft tumors generated from DSCAM-AS1-suppressed colorectal cancer cells, AKT3 expression has been shown to be decreased, while miR-384 level has been increased, demonstrating the role of DSCAM-AS1 in enhancement of AKT3 levels through modulation of expression of miR-384." (PMID 34708048, 2021).
schizophrenia (24 papers, 2017 to 2026). A major psychotic disorder characterized by abnormalities in the perception or expression of reality. "Genes that were associated with brain volumes, depression, and schizophrenia or bipolar disorder includedAC011997.1,AKT3,BANK1,BOLL,DCC,HSPD1,HSPE1,HSPE1-MOB4,MOB4,PLCL1,RFTN2,SF3B1, andTRPS1." (PMID 40800518, 2024). "All schizophrenia-linked SNPs in the chromosomal region centered around AKT3 map within the AKT3 gene itself." (PMID 35525984, 2022). "A strong association between single-nucleotide polymorphisms (SNPs) in the AKT3 gene and schizophrenia susceptibility was found by genome-wide association studies (GWAS) conducted by the Schizophrenia Working Group of the Psychiatric Genomics Consortium." (PMID 35525984, 2022). "The detection of a functionally hypoactive AKT3 mutation in a patient with schizophrenia, combined with the GWAS results linking AKT3 SNPs with schizophrenia, suggested a link between the AKT3 gene and schizophrenia." (PMID 35525984, 2022). "One major element of the Akt pathway found in the network is AKT3 (AKT Serine/Threonine Kinase 3), which is also an eQTL gene implicated in schizophrenia via GWAS." (PMID 35886854, 2022). "Genome-wide association studies (GWAS) link single nucleotide polymorphisms (SNPs) in AKT3 to schizophrenia (Schizophrenia Working Group of the Psychiatric Genomics 2014)." (PMID 34296180, 2021). "On the other hand, Akt1 and Akt3 have been identified as possible susceptibility genes for schizophrenia and Akt2 has been associated with anxiety- and depression-like behaviors." (PMID 31871542, 2019). "In summary, our study validates the essential role of Akt3 in the attainment of normal brain size and reveals a critical role for Akt3 in prefrontal cortical-hippocampal mediated cognitive function relevant to genetic risk for schizophrenia." (PMID 28467426, 2017). "They reported instead that only Akt3 represents a potential contributor to schizophrenia with a high risk factor of 64 out of 108 conservatively defined loci that meet genome-wide significance." (PMID 28442992, 2017). "This is particularly important for study of Akt3 function, given that SDCCAG8, a gene also implicated in schizophrenia, flanks Akt3 both in humans and mouse and shares regulatory regions." (PMID 28467426, 2017). "Study of the effects of schizophrenia-risk associated AKT3 polymorphisms (as previously done for AKT1) on neuroanatomical structure and neurocognitive function in normal human subjects, is warranted." (PMID 28467426, 2017). "Here, we investigated the role of AKT3 as it relates to aspects of learning and memory and behavioral function, relevant to schizophrenia and cognitive disability, utilizing a novel murine model of Akt3 genetic deficiency." (PMID 28467426, 2017). "It is noteworthy that recent human genetic studies are in accord with our data and suggest that impaired Akt3 is associated with schizophrenia, depression and anxiety endophenotypes." (PMID 28442992, 2017). "Altogether, these comprehensive behavioral manifestations propose that Akt3 signaling contributes to the normal functioning of the neural circuitry intervening in the symptoms associated with schizophrenia, depression and anxiety." (PMID 28442992, 2017). "In addition, injured AKT3 genes have been associated with psychiatric illnesses including schizophrenia." (PMID 30781836, 2019). "Therefore, we hypothesized that the AKT3-Q60H mutant may be functionally defective and have a causative role in the pathophysiology of schizophrenia." (PMID 35525984, 2022). "Genetic variation in the AKT3 locus (chr1:243503719–244002945) is a top GWAS signal in schizophrenia and pathway analysis identified 50 single nucleotide polymorphisms (SNPs) within the AKT3 gene that contribute to four of the top pathways associated with risk for schizophrenia and bipolar disorder." (PMID 28467426, 2017).